MBNL1 (muscleblind like splicing regulator 1)
Diseases named in the same sentence as MBNL1 in open-access papers (continued):
Sharing a sentence is not in itself a finding about the gene and the disease.
diabetes (4 papers, 2016 to 2024). "In vivo studies revealed that Hdac3 knockdown or Mbnl1 overexpression alleviated diabetes symptoms through circMlxipl-regulated ChREBP in diabetic mice." (PMID 39580381, 2024). "Collectively, these findings indicate that Hdac3 knockdown or Mbnl1 overexpression alleviated diabetes symptoms, possibly through circMlxipl-regulated ChREBP in vivo." (PMID 39580381, 2024). "Further investigation is needed to examine if MBNL1 levels are decreased in beta cells of diabetic mice and humans and how MBNL1 levels are connected to beta cell survival in diabetes." (PMID 27526875, 2016). "Our results suggest that the metformin/MBNL1/miR-130a-3p/STAT3 pathway is involved in regulating the senescence and pathological changes in renal tubular epithelial cells in diabetes." (PMID 32104542, 2020). "Our study results indicate that MBNL1, miR-130a-3p, and STAT3 may become new targets for treating diabetic renal tubular lesions." (PMID 32104542, 2020). "Furthermore, our preliminary data also revealed that Mbnl1 was downregulated in diabetic mouse model and lipotoxic β-cells, suggesting that Mbnl1 might act as an RBP of pre-Mlxipl to regulate β-cell failure in diabetes." (PMID 39580381, 2024).
gastric cancer (4 papers, 2021 to 2024). A primary or metastatic malignant neoplasm involving the stomach. "MBNL1 is downregulated in breast cancer, leukemia, stomach cancer, esophageal cancer, glioma, and Huntington’s disease." (PMID 36064939, 2022). "Eventually, TCEAL2 and MBNL1 were proved to be differentially regulated by CREB1 during tumorigenesis of gastric cancer." (PMID 35421923, 2022). "We therefore proposed TCEAL2 and MBNL1 as potential therapeutic targets for gastric cancer." (PMID 35421923, 2022). "Muscleblind-like splicing regulator 1 (MBNL1), one of the members of the MBNL protein family, has been negatively correlated with poor prognosis in breast, lung, and gastric cancers, and inhibits the recurrence and metastasis of triple-negative breast cancer." (PMID 36064939, 2022).
glioma (4 papers, 2021 to 2025). A benign or malignant brain and spinal cord tumor that arises from glial cells (astrocytes, oligodendrocytes, ependymal cells). "It stabilizes the mRNAs of BUD13 and CDK12, thereby promoting MBNL1 phosphorylation and subsequently facilitating the formation of glioma vasculogenic mimicry (VM)." (PMID 40469294, 2025). "The specific mechanism involves METTL3 stabilizing the mRNAs of BUD13 and CDK12, leading to their overexpression, which in turn promotes the phosphorylation of MBNL1 and facilitates the VM process in gliomas." (PMID 40469294, 2025). "In malignant gliomas, hypoxic conditions impede the nuclear transport of MBNL1 by strengthening the exclusion of exon 5 of MBNL1, thereby promoting glioma cell stemness." (PMID 38725048, 2024). "MBNL1 protein levels in glioma tissues were significantly decreased and negatively correlated with pathological grades." (PMID 36064939, 2022). "MBNL1 inhibits glioma stem cell self-renewal and tumorigenic potential, hypoxic response within the tumor inhibits MBNL1 activity, promoting stem-like phenotypes and tumor growth." (PMID 34659561, 2021).
heart failure (4 papers, 2021 to 2024). Inability of the heart to pump blood at an adequate rate to meet tissue metabolic requirements. "This suggests that the sustained high concentration of MBNL1 may contribute to heart failure via Myocardin and TNF‐α." (PMID 33295096, 2021). "All 14 RBPs differentially expressed between heart failure and healthy adult heart were also significantly differentially expressed between iPSC-CVPC and healthy adult heart, although three had opposite directions of effect (HNRNPL, MBNL1, SAMD4A)." (PMID 35226669, 2022).
Insulin resistance (4 papers, 2020 to 2025). Increased resistance towards insulin, that is, diminished effectiveness of insulin in reducing blood glucose levels. "These splicing events are directly regulated by MBNL1, and several of them have been linked to clinically relevant phenotypes in DM1, such as reduced dorsiflexion strength, impaired Ca2+ homeostasis, and insulin resistance in DM1 patients." (PMID 40896579, 2025). "Moreover, Hdac3 knockdown or Mbnl1 overexpression significantly improved HFD-induced insulin resistance and glucose intolerance." (PMID 39580381, 2024).
prostate carcinoma (4 papers, 2017 to 2022). A carcinoma that arises from epithelial cells of the prostate gland. "MBNL1 (muscleblind-like splicing regulator 1) is a tumor suppressor factor that was found downregulated in different cancers, including prostate cancer." (PMID 35954483, 2022). "In addition, MBNL1 inhibits the migration and invasion of prostate cancer cells, exerting tumor-suppressive effects." (PMID 36064939, 2022). "Interestingly, recent data points to a key role for RBFOX2 and MBNL1 who seem to account for numerous splicing alterations in various cancers including breast, lung, and prostate cancer." (PMID 28493890, 2017). "Thus, DDX5 overexpression in prostate cancer might lead to the inhibition of the oncosuppressor activity of MBNL1." (PMID 35954483, 2022). "In addition, MBNL1 itself does not appear to be considerably mutated, amplified, or deleted in the prostate cancer datasets analyzed." (PMID 30456384, 2018). "As for MBNL1, the overexpression of DDX5 in prostate cancer could play a crucial role in the deregulation of the activity of RBFOX2 leading to cancer progression." (PMID 35954483, 2022).
spinocerebellar ataxia type 8 (4 papers, 2014 to 2022). Spinocerebellar ataxia type 8 (SCA8) is a subtype of type I autosomal dominant cerebellar ataxia (ADCA type I) characterized by cerebellar ataxia and cognitive dysfunction in almost three quarters of patients and pyramidal and sensory signs in approximately a third of patients. "In Spinocerebellar ataxia type 8 (SCA8), bi-directional expression of CAG-CTG expansion results in CUG-containing RNA, which misregulates MBNL1 and CUGBP1." (PMID 36142405, 2022).
cardiomyopathy (3 papers, 2015 to 2025). A disease of the heart muscle or myocardium proper. "Collectively, these data suggest that MBNL1 is a critical factor underlying the acute wound-healing process, as loss of this gene product renders mice more susceptible to ventricular wall rupture and greater cardiomyopathy in surviving mice, consistent with impaired myofibroblast differentiation." (PMID 26670661, 2015). "Although Mbnl1∆E3/∆E3 mice do not exhibit overt cardiomyopathy, loss of MBNL1 function in the papillary muscles could predispose the mice to tricuspid and mitral valve failure." (PMID 26472242, 2015).
dilated cardiomyopathy (3 papers, 2019 to 2025). Cardiomyopathy which is characterized by dilation and contractile dysfunction of the left and right ventricles. "In addition, upregulation of Kcna4 and downregulation of Ckmt2, genes linked to dilated cardiomyopathy and arrhythmia, have been observed in cardiac-specific MBNL1 and MBNL2 double-knockout mice and were also misregulated in CUG960 +dox mice." (PMID 39932794, 2025). "Mice overexpressing CELF1 in the heart show conduction abnormalities and dilated cardiomyopathy thus confirming the contribution of MBNL1 sequestration and CELF1 up‐regulation to DM1 pathogenesis." (PMID 36852954, 2023). "We identified genes that have previously been implicated in heart development and structural heart malformations (e.g. MBNL1, ROR1), and known disease-related genes (e.g. NEXN, dilated cardiomyopathy; NDUFS1, mitochondrial complex I deficiency)." (PMID 31314787, 2019). "Indeed, Mbnl1 knockout mice develop muscle myotonia, weakness/wasting, and cardiac defects including dilated cardiomyopathy and heart conduction block." (PMID 36852954, 2023).
fragile X-associated tremor/ataxia syndrome (3 papers, 2013 to 2021). Fragile X-associated tremor/ataxia syndrome (FXTAS) is a rare neurodegenerative disorder characterized by adult-onset progressive intention tremor and gait ataxia. "Thus, recent studies have found Sam68 colocalized with MBNL1 (muscle blind-like), and hnRPN G proteins within CGG mRNA aggregates, which are supposed to play a role in the regulation of AS in Fragile X-associated tremor/ataxia syndrome (FXTAS)." (PMID 24287914, 2013).
Anxiety (2 papers, 2010 to 2025). Intense feelings of nervousness, tension, or panic often arise in response to interpersonal stresses. "Since Mbnl1−/− mice showed increased thigmotaxis, but the cause of this anxiety-related behavior is unclear, we further tested these mutants in the elevated plus maze, another anxiety test." (PMID 20360842, 2010). "To investigate the contribution of these genes to cognitive symptoms observed in DM1 patients, we studied the effect of deletion of Six5, Dmpk and Mbnl1 on three separate behavioral tasks designed to test learning and memory, anxiety and motivation." (PMID 20360842, 2010). "In a second test of anxiety, the elevated plus maze, the Mbnl1−/− mice showed conflicting signs of increased and decreased anxiety." (PMID 20360842, 2010). "We tested all three mutant mouse strains for alterations in anxiety levels and only Mbnl1−/− mice exhibited high levels of thigmotaxis, a behavior indicative of anxiety." (PMID 20360842, 2010). "Loss of MBNL proteins resulted in structural and morphological changes in brains of mice and significant differences in MBNL1 gene expression were found in mice expressing anxiety–depression-like behavior." (PMID 38092990, 2025). "However, Mbnl1−/− mice also made fewer head dips over the side of the maze, which normally indicates increased anxiety." (PMID 20360842, 2010). "Similarly, the Mbnl1−/− mice spent less time in the stretch position which is typically indicative of decreased anxiety." (PMID 20360842, 2010). "Taken together with the Open Field phenotype, these results are inconclusive as to whether or not the Mbnl1−/− mice experience increased anxiety and but do indicate that the mutant mice have musculoskeletal deficits." (PMID 20360842, 2010).
Diabetic Nephropathy (2 papers, 2020 to 2024). "Our results suggest that metformin reduces the senescence of renal tubular epithelial cells in diabetic nephropathy via the MBNL1/miR-130a-3p/STAT3 pathway, which provided new ideas for the therapy of this disease." (PMID 32104542, 2020). "In addition, more recent studies have also reported that Mbnl1 ameliorates diabetic nephropathy via miR-130a-3p/STAT3 axis in response to Metformin." (PMID 39580381, 2024). "We firstly explored the endogenous expression of MBNL1, miR-130a-3p, and STAT3 in diabetic nephropathy and their relation with the senescence of renal tubular epithelial cells." (PMID 32104542, 2020).
Duchenne muscular dystrophy (2 papers, 2023 to 2025). Duchenne muscular dystrophy (DMD) is a neuromuscular disease characterized by rapidly progressive muscle weakness and wasting due to degeneration of skeletal, smooth and cardiac muscle. "It has been shown before by qPCR that many “DM1-specific” splice events are shared between DM1 and Duchenne muscular dystrophy (DMD) including, among others, MBNL1, ATP2A1, TTN, TNNT2 and MEF2A/C." (PMID 40149583, 2025).
Huntington disease (2 papers, 2022 to 2025). Huntington disease (HD) is a rare neurodegenerative disorder of the central nervous system characterized by unwanted choreatic movements, behavioral and psychiatric disturbances and dementia. "For example, 1 × 1 A:A internal loops observed in RNA CAG repeat expansions causing Huntington’s disease are known to interact with muscleblind-like 1 protein (MBNL1)." (PMID 39711475, 2025).
left ventricular hypertrophy (2 papers, 2013 to 2016). Enlargement of the LEFT VENTRICLE of the heart. "MRI analysis of Mbnl1−/−; Mbnl2+/− KOs revealed atrial dilatation and left ventricular hypertrophy." (PMID 24293317, 2013).
melanoma (2 papers, 2023 to 2025). A malignant, usually aggressive tumor composed of atypical, neoplastic melanocytes. "We generated CRISPR-Cas9 knockout models of Mbnl1 (“1KO”) and Mbnl2 (“2KO”) in B16-F10 melanoma cells." (PMID 40305509, 2025). "In this study, we found six mitochondria-related genes, BTG2, CP, LRIG1, CYP1A1, GBP2, and MBNL1, which might be targets of quercetin in melanoma and play crucial roles in melanoma." (PMID 37869567, 2023). "Combining the results of RNA-seq, molecular docking, and bioinformatics analysis, we found six mitochondria-related genes, BTG2, CP, LRIG1, CYP1A1, GBP2, and MBNL1, which might be targets of quercetin in melanoma and provide an available targeting therapy strategy for melanoma." (PMID 37869567, 2023). "In mouse melanoma, this was first revealed through a CRISPR knockout screen, where Mbnl1 and Mbnl2 emerged as top hits conferring tumor resistance to cytotoxic T cell-mediated killing." (PMID 40305509, 2025).
viral infection (2 papers, 2023). "Moreover, several novel genes score in the top 20 for multiple strains, including UBE2M, MBNL1, FBXW7, PCGF1, and PPP2CA, implicating those gene products in processes important for viral infection across HIV-1 strains." (PMID 36744886, 2023). "Besides the splicing regulators MBNL1 and sUGP2, cluster 7 contains members of the ELAVL family, previously shown to be prone to be hijacked during viral infections." (PMID 36814457, 2023).
atherosclerosis (1 paper, 2021). A disease characterized by the build-up of fatty material and calcium deposition in the arterial wall resulting in partial or complete occlusion of the arterial lumen. "The expression of MBNL1 and Abelson interactor 1 (Abi1) splice variants (Abi1‐e10 and Abi1‐Δe10) was compared between artery tissues from healthy donors and atherosclerosis patients." (PMID 33759281, 2021). "Loss of MBNL1 was found in the macrophage‐like VSMC (VSMC‐M) in artery wall from atherosclerosis patients." (PMID 33759281, 2021). "Loss of MBNL1 significantly induces the Abi1‐Δe10 isoform expression by alternative splicing in the macrophage‐like VSMC (VSMC‐M) in artery wall from atherosclerosis patients." (PMID 33759281, 2021). "We profiled the mRNA level of these factors and found that the change of MBNL1 mRNA level was the most significant between control and atherosclerosis arteries." (PMID 33759281, 2021).
B-cell lymphoma (1 paper, 2023). "Taken together, SC-1 represents a triple-hit B-cell lymphoma cell line, in which IGH rearrangements target FL-specific oncogene BCL2, MYC, as well as a novel target at 17q21, together with fusion of BCL6 and MBNL1." (PMID 37371852, 2023). "Taken together, SC-1 carries three major rearrangements resulting in the gene fusions IGH::BCL2, IGH::MYC, and MBNL1::BCL6 which were characterized cytogenetically, genomically, and at the transcript level, thus, representing an exceptionally well characterized triple-hit B-cell lymphoma cell line." (PMID 37371852, 2023).
Brain atrophy (1 paper, 2021). Partial or complete wasting (loss) of brain tissue that was once present. "Thus, Mbnl1 heterozygosity, in conjunction with Mbnl2 loss, results in global brain atrophy with increased apparent ventricle volumes and widespread white and gray matter volume reductions in the mouse brain at four months of age." (PMID 34848815, 2021).
breast tumors (1 paper, 2023). "High MBNL1 expression level in human breast tumors was found to be associated with reduced metastatic relapse likelihood and survival and promote tumor progression." (PMID 37189064, 2023).
cortical cataract (1 paper, 2016). A cataract (disease) that involves the lens cortex. "Taken together these data are consistent with Mbnl338kD and Mbnl1 deficits playing an important role in the development of the posterior subcapsular and cortical cataracts observed in DM1." (PMID 27484195, 2016).
COVID-19 (1 paper, 2023). A disease caused by infection with severe acute respiratory syndrome coronavirus 2. "Lastly, we linked RBPs to functional, OMICs and COVID-19 patient data from other studies, and identified MBNL1, FTO and FXR2 RBPs as potential clinical biomarkers." (PMID 36814457, 2023).
endometriosis (1 paper, 2023). The growth of functional endometrial tissue in anatomic sites outside the uterine body. "Through scRNA-seq, WGCNA, and LASSO methodologies, DES, GREM1, MBNL1, and AEBP1 emerged as crucial core genes linked to tissue stem cell markers in endometriosis." (PMID 38115253, 2023). "By employing scRNA-seq, WGCNA, and LASSO diagnostic model development methodologies, DES, GREM1, MBNL1, and AEBP1 were identified as pivotal core genes in endometriosis that display notable associations with tissue stem cell marker genes." (PMID 38115253, 2023).
lymphoblastic leukemias (1 paper, 2020). "We began by examining the intersection of these gene expression signatures, and found that MBNL1 expression was a common feature of these signatures across both acute myeloid and lymphoblastic leukemias." (PMID 32398749, 2020).
middle ear cholesteatoma (1 paper, 2024). "The interaction network of the the 2 most upregulated (hsa-miR-21-5p and hsa-miR-142-5p) and 3 most downregulated (hsa-miR-508-3p, hsa-miR-509-3p and hsa-miR-211-5p) miRNAs identified TGFBR2, MBNL1, and NFAT5 as potential key target genes in middle ear cholesteatoma." (PMID 38890701, 2024). "The interaction network analysis of the two most upregulated miRNAs (hsa-miR-21-5p and hsa-miR-142-5p) and the three most downregulated miRNAs (hsa-miR-508-3p, hsa-miR-509-3p, and hsa-miR-211-5p) identified TGFBR2, MBNL1, and NFAT5 as potential key target genes in middle ear cholesteatoma." (PMID 38890701, 2024).
muscular atrophy (1 paper, 2023). The loss of muscle tissue due to inactivity or disease. "Through a cis-regulatory module, lncMAAT increases the expression of neighboring gene Mbnl1, thereby preventing muscular atrophy." (PMID 37047345, 2023).
myocardial infarction (1 paper, 2015). Gross necrosis of the myocardium, as a result of interruption of the blood supply to the area, as in coronary thrombosis. "MBNL1 overexpression promotes transformation of fibroblasts into myofibroblasts, whereas loss of Mbnl1 abrogates transformation and impairs the fibrotic phase of wound healing in mouse models of myocardial infarction and dermal injury." (PMID 26670661, 2015).
Nephropathy (1 paper, 2020). A nonspecific term referring to disease or damage of the kidneys. "In db/db diabetic mice, we found an enhanced senescence level combined with low expression of MBNL1 and miR-130a-3p and high expression of STAT3 compared with db/m control mice during nephropathy development." (PMID 32104542, 2020).
Onset (1 paper, 2013). The age group in which disease manifestations appear. "Mbnl1 KO adults develop skeletal muscle myotonia and DM-associated muscle pathology, including centralized myonuclei and split fibres, but do not display either the hypotonia or adult-onset muscle wasting features of congenital or adult-onset DM, respectively." (PMID 24293317, 2013).
osteosarcoma (1 paper, 2022). A usually aggressive malignant bone-forming mesenchymal neoplasm, predominantly affecting adolescents and young adults. "The disassembly seen when using MBNL1 as a marker for SGs closely resembled that reported previously when using GFP-G3BP1 as a marker in human U-2 OS osteosarcoma cells, with breakdown of large SGs into much smaller fragments." (PMID 35642886, 2022).
ovarian carcinoma (1 paper, 2014). A malignant neoplasm originating from the surface ovarian epithelium. "Thus, four genes that were validated in respect to OS (MBNL1, SPPLB2, VAV2, and CLASP1) were further tested in the independent set of 30 ovarian cancer samples." (PMID 24478986, 2014).
pancreatic ductal adenocarcinoma (1 paper, 2025). An infiltrating adenocarcinoma that arises from the epithelial cells of the pancreas. "Extending the analysis to other cancer types, we discovered that MBNL1 expression also had a high positive correlation with CD8A expression for several other cancer types, including Testicular Germ Cell Tumors (TCGT) and Pancreatic Ductal Adenocarcinoma (PAAD)." (PMID 40305509, 2025).